SIRT1 (sirtuin 1)
Diseases named in the same sentence as SIRT1 in open-access papers (continued):
Sharing a sentence is not in itself a finding about the gene and the disease.
glioma (continued). "Overall, SIRT1’s modulation may influence glioma cell survival and proliferation, and SRT2183 has potential as a therapeutic agent against glioma by inducing growth inhibition and apoptosis, primarily through the activation of ER stress pathways." (PMID 40710366, 2025). "Moreover, SIRT1 contributes to glioma stem cell maintenance and microglia-mediated tumor support, suggesting its pivotal role in tumor progression and resistance mechanisms." (PMID 40710366, 2025). "It has been found that SIRT1 may promote glioma cell proliferation and inhibit apoptosis via the PTEN/PI3K/AKT signaling pathway." (PMID 39845013, 2025). "Studies shows SIRT1 in glioma has been a tumor-promoting role." (PMID 39845013, 2025). "In gliomas, SIRT1 plays a crucial role in the conversion of microglia into tumor-supporting cells." (PMID 40710366, 2025). "Overexpression of miR-376a leads to the inhibition of SIRT1, YAP1 (Yes-associated protein 1), and VEGF (Vascular Endothelial Growth Factor) expression, consequently suppressing the proliferation, migration, and angiogenesis of glioma cell lines." (PMID 40710366, 2025). "SIRT1 was discovered to be highly expressed in glioma cells positive for CD133." (PMID 38397988, 2024). "Additionally, Liu’s work sheds light on the impact of SENP1-mediated de-SUMOylation of SIRT1 in glioma development." (PMID 38801243, 2024). "In gliomas, studies have shown that SIRT1 activators can induce tumor cell apoptosis, suggesting that SIRT1 may be a potential target for glioma treatment." (PMID 39845948, 2024). "SIRT1 translational control is essential for CD133+ glioma stem cell development." (PMID 38397988, 2024). "In addition, miR34a-modified MSCs can not only induce glioma cell aging, but also induce DNA damage through regulation of Sirtuin 1 (SIRT1)." (PMID 37666813, 2023). "In addition, the Kaplan–Meier curve showed that SIRT1, SIRT3, and SIRT5 were closely associated with OS, DSS, and PFI of glioma patients, and other SIRT family members are related to the prognosis of glioma patients to varying degrees." (PMID 36568393, 2022). "Several studies found that SIRT1 exerts anti-cancer effects in gliomas." (PMID 36568393, 2022). "Moreover, the regulatory roles of NNMT, GAP43, and SIRT1 were confirmed in glioma xenograft mouse models." (PMID 35884600, 2022). "In conclusion, the role of miR-133b in modulating the development and metastasis of gliomas could be mediated by Sirt1 expression and could be a therapeutic target for glioma patients." (PMID 35071748, 2022). "Moreover, activation of SIRT-1 was reported to induce autophagic glioma cell death and inhibit cell viability." (PMID 36361680, 2022). "In addition, Sirt1 silencing was found to promote the sensitivity of the CD133+ cells in glioma tissue to radiotherapy, both in vivo and in vitro." (PMID 35071748, 2022). "Sirt1 was verified as a new direct target of miR-133b in U87 glioma cells." (PMID 35071748, 2022). "Sirt1 increased proliferation and suppressed apoptosis in glioma tissue." (PMID 35071748, 2022). "Whether Sirt1 could function as an oncogene in the pathogenesis of glioma was a major question in recent studies." (PMID 35071748, 2022). "This implies that hsa-circ-0076248, miR-181a, and SIRT1 may be viable therapeutic feasible targets for glioma." (PMID 35883576, 2022). "SIRT1 inhibition inhibited circ-0082374’s prognostic glioma-promoting action." (PMID 35883576, 2022). "Furthermore, Sirt1 mRNA was found to be considerably up-regulated in glioma samples, compared with adjacent healthy tissue, and had an inverse correlation with the level of miR-133b in tumor cells." (PMID 35071748, 2022). "In addition, circZNF609/miR-134-5p/BTG-2 axis and circ_0076248/miR-181a/SIRT1 axis have also been disclosed in glioma." (PMID 34057019, 2021).
glioma (continued). "In the same way, a different mixture of cinnamon rich in polyphenols exhibited important neuroprotective activities in rat glioma cells by suppression of pro-inflammatory cytokines, upregulation of sirtuin 1 (SIRT1) and activation of mitogen-activated protein kinase (MAPK) pathways." (PMID 34045956, 2021). "In another study, miR-133b was shown to suppress glioblastoma invasion and cell migration via downregulation of metalloproteinase 14 (MMP14) in U87 and U251 glioma cells, while miR-133b was also shown to impede proliferation and invasion of glioma due to Sirt1 downregulation." (PMID 34660740, 2021). "The effect of SIRT1 on glioma progression still needs more in vivo experiments to verify." (PMID 32373523, 2020). "However, currently there is a controversy in the published literature regarding the levels of expression versus prognostic and mechanistic roles of SIRT1 in gliomas and GBM, in particular." (PMID 32118205, 2020). "SIRT1 activator SRT2183 suppresses glioma cell growth and destroyed neurospheres in vitro." (PMID 32373523, 2020). "Importantly, the level of SIRT1 expression is gradually decreased with advanced pathology grade of glioma patients and is significantly lower than normal brain tissue." (PMID 31207928, 2019). "Given the inhibitory effects by SRT2183 on glioma cell growth, we examined whether SRT2183 affects the acetylation of STAT3 and NF-κB, two well-known substrates of Sirt1 in glioma cells." (PMID 31319814, 2019). "In addition, hsa_circ_0076248 and SIRT1 exhibited significantly higher expression in U87 and U251 glioma cell lines than HEB cell." (PMID 30506951, 2019). "Our study put forward to the regulatory mechanism among hsa_circ_0076248, miR‐181a, and SIRT1 in glioma growth and invasion and suggests that hsa_circ_0076248, miR‐181a, and SIRT1 may serve as potential therapeutic targets for glioma in the future." (PMID 30506951, 2019). "The expression of SIRT1 mRNA was significantly higher in glioma than that in normal brain tissues." (PMID 30506951, 2019). "Similarly, it was reported that miR-133 targeted SIRT1 in glioma cells, leading to inhibition of cell proliferation." (PMID 29487709, 2018). "Consequently, CD133+ glioma stem cells express high levels of SIRT1 compared to CD133‐ non‐stem cells." (PMID 28994177, 2017). "Further studies are needed to identify the roles of Sirtuin-1 and other sirtuins in the epigenetic modulation of glioma cells, and how these effects might be mediated." (PMID 28491867, 2017). "SIRT1 is required for both oncogenic transformation and maintenance of stemness in glioma cells." (PMID 28994177, 2017). "Knockout of Sirt1 also sensitized glioma CD133‐positive cells to ionizing radiation." (PMID 28609013, 2017). "Inhibition of SIRT1 activates apoptosis of CD133+ glioma cells, and CML LSCs." (PMID 25826085, 2015). "Concomitant inhibition of HDAC1 and activation ofHDAC4/SIRT1 may be salutary in restraining highly aggressive tumorprogression and may improve survival time in glioma patients." (PMID 25791281, 2015). "The CNVs for the other four LARs–KAT6B (10q), SIRT1(10q), HDAC10 (22q), and HDAC9 (7q)–were highly associated with the risk signature and may be affected in chromosomal alterations such as 10q−, 22q− and 7+ in gliomas." (PMID 33718432, 2021). "The role of SIRT1 in glioma may be related with PTEN/PI3K/Akt axis promoting tumorigenicity." (PMID 31119097, 2019). "In this study, the preliminary investigation on the function of hsa_circ_0076248 and the relationship among hsa_circ_0076248, miR‐181a, and SIRT1 will turn our eyes to noncoding RNA, especially circRNA, which may provide us with unexpected key on diagnosis and treatment of glioma." (PMID 30506951, 2019). "Several studies have shown that SIRT1 may promote tumorigenesis of glioma." (PMID 30953268, 2019).
glioma (continued). "In summary, our study sheds light on the regulatory mechanism of hsa_circ_0076248 in glioma growth and invasion via sponging miR‐181a, which downregulates the SIRT1 expression and also suggests that hsa_circ_0076248, miR‐181a, and SIRT1 may serve as potential therapeutic targets for glioma." (PMID 30506951, 2019). "More importantly, downregulating hsa_circ_0076248 could remarkably promote the TMZ chemotherapy sensitivity, block the cell cycle, depress the proliferation in vitro and in vivo, suppress glioma cell invasion, and upregulate the expression of SIRT1, while miR‐181a inhibitor could reverse the effect." (PMID 30506951, 2019). "Additionally, Qu’s group identified that SIRT1 might be a promoter of glioma growth through the PTEN/PI3K/AKT signaling pathway." (PMID 30953268, 2019). "Glucose influences the HMGB1 signaling pathway through SIRT1, where low SIRT1 levels due to high glucose result in the activation of HMGB1, promoting the proliferation, migration, and invasion of glioma cells while inhibiting apoptosis." (PMID 40710366, 2025). "SIRT1, SIRT3, SIRT5, and SIRT7 are often overexpressed and promote glioma cell proliferation, stemness, therapy resistance, and metabolic adaptation." (PMID 40710366, 2025). "CircRNAs also work as miRNA sponges to impact glioma apoptosis and subsequent TMZ sensitivity by regulating sirtuin 1 (SIRT1) expression." (PMID 39877636, 2025). "SIRT1 overexpression upregulates YAP1 and VEGF, promoting glioma cell proliferation, migration, and angiogenesis." (PMID 40710366, 2025). "The glioma xenograft mouse models were used to verify the regulatory role of NNMT, GAP43, and SIRT1." (PMID 35884600, 2022). "Schnekenburger and colleagues showed that their newly synthesized Compound 18 (identified via in silico screening, see Section 3.8) inhibits SIRT-1 and SIRT-2 with an anti-proliferative effect in glioma cells, both in in vitro and in vivo settings." (PMID 36080416, 2022). "Some studies have shown that SIRT1 and SIRT7 are upregulated and SIRT2 and SIRT3 are downregulated in glioma cells." (PMID 36139696, 2022). "In U373 and Hs683 glioma cells, treatment of Compound 18 increased acetylation levels of histone H4, histone H3K56, and α-tubulin, which confirmed cellular inhibition of SIRT1 and SIRT2." (PMID 34650436, 2021). "HDAC-related genes upregulated in IDH1/2mut glioma include HDAC2/4/5, KDM1A, CHD4, MTA2/3, SIRT1/2, PHF21A, and BRMS1L." (PMID 34424450, 2021). "The results showed a significant positive correlation between SIRT1 and CUL4B expression and lymphoid neoplasm diffuse large B-cell lymphoma, brain lower grade glioma, pancreatic adenocarcinoma, and thymoma." (PMID 34163012, 2021). "Previous studies indicated that circ_0034642 and circ_0076248 promoted glioma proliferation and invasion in the miR-1205/BATF3 axis and miR-181a/SIRT1 axis, respectively." (PMID 32061256, 2020). "Consistently, SIRT1 expression was clearly increased in F3.EGFRviii spheres, along with OLIG2, which has recently been characterized in glioma and GSCs." (PMID 28830458, 2017). "Along the same line, glioma samples (ODsand GL) with high HDAC4 and SIRT1 expression were metabolomicallydifferent from samples with low HDAC4 and SIRT1 expression, thelatter having a significantly lower GPChol/PChol ratio than the former group(respectively)." (PMID 25791281, 2015). "Additionally, miR-376a directly regulates the expression of SIRT1 in glioma cells, thereby suppressing the VEGF signaling pathway and ultimately inhibiting glioma cell proliferation." (PMID 41300698, 2025). "Experimental studies in glioma models revealed that SIRT6 overexpression suppresses tumor growth by promoting histone deacetylation and cell-cycle arrest, whereas SIRT1 limits androgen biosynthesis through FOXO1 deacetylation, thereby restraining tumor progression." (PMID 41425553, 2025). "SIRT1 is aberrantly localized in the cytoplasm of glioma cells, unlike its typical nuclear localization in normal cells." (PMID 40710366, 2025).
glioma (continued). "In a prior study, tissue analysis revealed the overexpression of SIRT1 in glioma tissues in comparison to nontumour tissues." (PMID 38597418, 2024). "Procyanidin exhibited neuroprotective activity by its capacity to regulate the secretion of S100 via the regulation of SIRT1 and the suppression of TNF-γ, NF-kB p65 (RelA subunit of NF-κB family of transcription factors) and B-cell lymphoma 2 (Bcl-2) on glioma cells." (PMID 34045956, 2021). "Glioma cells surrounding cavernous vessels (top row) as well as in peri-necrotic glioma regions (second row) observed on H&E show higher SIRT1 expression, as compared to non-hypoxic or less hypoxic-appearing surrounding tumor regions." (PMID 32118205, 2020). "In addition, SIRT1 promotes nuclear accumulation of β-catenin protein while MSC-derived exosomes carrying miR-133b attenuate glioma cell development via disrupting the Wnt/β-catenin signaling pathway." (PMID 32655835, 2020). "We analyzed SIRT1, CCL2, VCAM-1 and ICAM-1 in human glioma cell lines by immunoblotting." (PMID 31207928, 2019). "In conclusion, modified amounts of active SIRT1, IDH1 and MDH1 in gliomas may interfere with acetyl-CoA production." (PMID 21655185, 2011). "As a consequence of the absence of SIRT1 in gliomas, ACSS2-dependent production of acetyl-CoA from acetate will be aborted." (PMID 21655185, 2011). "Regarding the oxidative stress response, nicotinamide rescues normal astrocytes from oxidative stress induced by hydrogen peroxide (H2O2), but it does not have the same protective effect on glioma cells, indicating a context-dependent role of SIRT1 in managing oxidative stress." (PMID 40710366, 2025). "Depletion of SIRT1 leads to a marked reduction in cell growth and an increase in apoptosis in these cancerous neural stem cells, but this effect is not observed in the U87 glioma cell line, suggesting a specific role in cancer cells with neural stemness." (PMID 40710366, 2025). "In glioma, miR-34a suppresses cell cycle progression and proliferation of glioma cells through direct inhibition of the expression of MET receptor tyrosine kinases (c-MET RTK), Notch-1, Notch-2, cyclin-dependent kinase 6 (CDK6), cyclin 1 (CCND1), and silent information regulator 1 (SIRT1)." (PMID 35922753, 2022). "The roles of SIRT1, SIRT2, SIRT3, and SIRT7 in glioma are not comprehensively understood." (PMID 36568393, 2022).
acute kidney injury (73 papers, 2010 to 2026). Sudden and sustained deterioration of the kidney function characterized by decreased glomerular filtration rate, increased serum creatinine or oliguria. "Moreover, numerous lines of evidence show that SIRT1 is implicated in principal complications of renal failure, including coronary artery disease, left ventricular hypertrophy, and CKD-MBD." (PMID 41009597, 2025). "Recent work has implicated SIRT1 as a protective factor in cisplatin-induced acute kidney injury." (PMID 35874713, 2022). "NMN rescues age-associated susceptibility to acute kidney injury via a SIRT1-dependent pathway." (PMID 31000692, 2019). "Given SIRT1’s established role in renal protection, inflammation, and oxidative stress, further prospective studies incorporating serial measurements and functional endpoints are warranted to better define its diagnostic and prognostic utility in acute kidney injury." (PMID 40507714, 2025). "Recently, we have demonstrated that serum SIRT1 concentration is considerably higher in patients with renal failure on maintenance hemodialysis in comparison to healthy subjects." (PMID 41009597, 2025). "Exposure to this chemical also suppresses SIRT1 expression, whereas resveratrol-mediated activation of SIRT1 mitigates sodium arsenite-induced acute kidney injury by enhancing mitophagy." (PMID 40705152, 2025). "Preclinical studies have shown that SIRT1 activation protects against ischemia-reperfusion injury, suggesting its potential as a biomarker or therapeutic target in acute kidney injury." (PMID 40507714, 2025). "Curcumin also exhibited protective effects in a rat model of gentamicin-induced acute kidney injury by reducing tubular cell apoptosis, oxidative stress, and inducing SIRT1 and Nrf2/HO-1 expression." (PMID 37630770, 2023). "The pharmacological activation of SIRT1 protects against ischemia/reperfusion-induced acute kidney injury." (PMID 35386302, 2022). "SIRT1 inhibits the release of inflammatory factors via NF-κBp65 deacetylation in septic rats with acute kidney injury." (PMID 35386302, 2022). "In acute kidney injury model, anti-TNFα, antioxidant activities and acute pharmacologic activation of SIRT1 induces reno-vasodilatation, increases renal blood flow (RBF) and decreases RVR." (PMID 33513830, 2021). "SIRT1 also plays a protective role in acute kidney injury; increased ROS and mitochondrial damage are necrosis features in AKI." (PMID 34746831, 2021). "In colitis and acute kidney injury models, activation of SIRT1 attenuates the TNFα-mediated intestinal and renal abnormalities." (PMID 33513830, 2021). "By increasing peroxisome function, SIRT1 activation, which is reciprocally stimulated by upregulated PPARα and PPARδ, can prevent the drug-induced renal cell apoptosis and acute kidney injury in mice." (PMID 31321239, 2019). "In this study, we showed that Sirt1 activation by SRT1720 significantly attenuated acute renal failure and histopathological alterations in cisplatin-treated mice through suppression of apoptotic cell death, oxidative stress, and inflammation." (PMID 31431003, 2019). "It was recently reported that Sirt1 overexpression in kidney tubule ameliorates cisplatin-induced acute kidney injury (AKI)." (PMID 31431003, 2019). "This study focused on the point that whether melatonin is protective in acute kidney injury (AKI) induced by severe burns and whether the protective effects are associated with the activation of SIRT1." (PMID 27599451, 2016). "Taken together, the TFs has significantly nephroprotective effect against IRI by affecting Sirt1/Nrf2/NF-κB signaling pathway, which should be developed as a new therapeutic agent or food additives to treat acute kidney injury in the future." (PMID 27455216, 2016).